AQP10 (aquaporin 10)
Description:
Aquaglyceroporins form homotetrameric transmembrane channels, with each monomer independently mediating glycerol and water transport across the plasma membrane along their osmotic gradient. Could also be permeable to urea. Among aquaglyceroporins, it exhibits a unique pH-gated glycerol transport activity, being more active at acidic pH. It most likely plays a central role in the efflux of glycerol formed during triglyceride hydrolysis in adipocytes and in glycerol uptake by enterocytes, as both processes occur and are stimulated at acidic pH.
Synonyms: AQPA_HUMAN
Tractability: Small molecule: a structure with a bound ligand is known. Antibody: UniProt places it where antibodies can reach, with high confidence; its Gene Ontology location is reachable by antibodies, with high confidence; UniProt predicts a signal peptide or a membrane-spanning region; the Human Protein Atlas places it where antibodies can reach.
Gene: Protein-coding gene on chromosome 1 (154,321,090 to 154,325,325, forward strand). Ensembl gene ENSG00000143595.
Subcellular location: Apical cell membrane; Cell membrane; Lipid droplet
Subcellular location (Human Protein Atlas): Plasma membrane; Vesicles
Pathways (Reactome):
Transport of small molecules: Passive transport by Aquaporins
Gene Ontology:
Molecular function: glycerol channel activity; protein binding; water channel activity; urea transmembrane transporter activity; channel activity
Biological process: glycerol transmembrane transport; protein homotetramerization; response to toxic substance; water transport; transmembrane transport; urea transmembrane transport
Cellular component: apical plasma membrane; lipid droplet; plasma membrane; basolateral plasma membrane; membrane
Genetic constraint (gnomAD): Loss-of-function variants: 15 observed, 23.31 expected, observed/expected ratio (o/e) 0.64, 90% interval 0.43 to 0.99. The upper end of that interval is the gene's LOEUF score, 0.99, which puts it in group 4 of 6, group 1 being the genes least tolerant of losing a copy. Missense variants: 256 observed, 370.18 expected, observed/expected ratio (o/e) 0.69, 90% interval 0.62 to 0.77. Synonymous variants: 139 observed, 155 expected, observed/expected ratio (o/e) 0.9, 90% interval 0.78 to 1.03.
Homologues: Orthologues: chimpanzee AQP10 (99% identical), macaque AQP10 (97% identical), dog AQP10 (86% identical), guinea pig AQP10 (84% identical), rat Aqp10 (79% identical), rabbit AQP10 (79% identical), pig AQP10 (78% identical), tropical clawed frog aqp10 (60% identical), zebrafish aqp10a (45% identical), Caenorhabditis elegans aqp-2 (36% identical), zebrafish aqp10b (35% identical), Drosophila melanogaster Drip (22% identical), and 6 more. Paralogues in human: AQP9 (46% identical), AQP3 (45% identical), AQP7 (39% identical), AQP7B (36% identical), MIP (21% identical), AQP2 (21% identical), AQP5 (20% identical), AQP4 (20% identical), AQP8 (20% identical), AQP1 (19% identical), AQP6 (19% identical).
Diseases named in the same sentence as AQP10 in open-access papers:
AQP10 is named in the same sentence as 18 diseases in open-access papers, as found by Europe PMC text mining. Sharing a sentence is not in itself a finding about the gene and the disease. The quoted sentences say what the papers report.
breast carcinoma (3 papers, 2022 to 2023). "The fourth aquaglyceroporin, AQP10, was omitted from this analysis since transcriptomic analysis indicated that AQP10 expression was unchanged in breast cancer biopsies." (PMID 37681917, 2023). "Until now, AQP10 mRNA has been found in several cancers, such as breast cancer and ovarian cancer." (PMID 35972604, 2022). "Transcriptomic analysis revealed that the three aquaglyceroporins, AQP3, AQP7 and AQP9, but not AQP10, are overexpressed in human breast cancer." (PMID 37681917, 2023).
Obesity (3 papers, 2013 to 2022). Accumulation of substantial excess body fat. "(II) AQP10: Aquaglyceroporins, such as AQP10, represent novel additional pathways for the transport of glycerol in human adipocytes, and the deregulation in the expression of aquaglyceroporins in adipose tissue is associated with human obesity." (PMID 29132311, 2017). "In conclusion, the present study demonstrates on one hand the expression of AQP7 in human adipocyte plasma membrane and on the other hand the presence of an alternative glycerol channel, AQP10, that working with AQP3 and AQP7 ensures glycerol exit from adipocyte, thus protecting humans from obesity." (PMID 23382902, 2013). "Human AQP10 has been suggested to be a target for obesity and metabolic diseases but could not be studied in the house mouse where the gene has been pseudogenized." (PMID 36344967, 2022).
gastric cancer (2 papers, 2018 to 2022). A primary or metastatic malignant neoplasm involving the stomach. "However, from the ‘KM plotter’ database, we determined that AQP10 mRNA expression was associated with poor survival in all gastric cancer patients involving both histological subtypes (intestinal and diffuse), male gender and in stages I and III patients." (PMID 29678898, 2018). "In which, we revealed AQP3, AQP9, and AQP11 mRNA expression were associated with improved OS in all gastric cancer patients especially with intestinal subtypes, whereas AQP0, AQP1, AQP4, AQP5, AQP6/2L AQP8, and AQP10 mRNA expression were associated with poor OS in all gastric cancer patients." (PMID 29678898, 2018). "Evidently, the association between AQP10 in gastric cancer is not known yet." (PMID 29678898, 2018). "Abnormal expression of AQP10 and AQP11 was reported in gastric cancer, but the regulatory mechanism demanded prompt solution." (PMID 36254092, 2022). "Intriguingly, AQP3 mRNA expression was associated with better OS with positive and negative HER2 in gastric cancer patients, whereas AQP9 and AQP10 mRNA levels were associated with better OS with negative HER2." (PMID 29678898, 2018). "In the present analysis, we revealed that AQP2, AQP6, AQP9, and AQP10 proteins were not expressed both in normal and gastric cancer tissues." (PMID 29678898, 2018). "In addition, AQP10 and AQP5 mRNA expression with positive HER2 and AQP1 and AQP2 mRNA with negative HER2 were associated with poor survival in gastric cancer patients." (PMID 29678898, 2018). "Indeed, in the HPA database, differentials in AQP10 protein expression between normal and gastric cancer tissue were also not detected." (PMID 29678898, 2018).
lung carcinoma (2 papers, 2016 to 2019). "Some genes with hypermethylated promoters have been reported in lung cancer, such as GAS7, AQP10, HLF, and HOPX." (PMID 30867848, 2019).
ovarian carcinoma (2 papers, 2018 to 2022). A malignant neoplasm originating from the surface ovarian epithelium. "AQP10’s high mRNA expression was found to be associated with better OS for all ovarian cancer patients, HR = 0.72 (0.57–0.9), P=0.0039." (PMID 29472315, 2018). "Subsequent expression of AQP0, AQP5, and AQP10 mRNA expression had better OS in grade I ovarian cancer patients." (PMID 29472315, 2018). "In general, our results showed that the presence of AQP10 and AQP11 mRNA linked with positive outcomes in ovarian cancer patients." (PMID 29472315, 2018). "On the other hand, mRNA expression of AQP1 (grades I and II), AQP4 (grades I, II, and III), AQP6/2L (grade I), AQP10 (grade II) showed a worse OS in ovarian cancer patients." (PMID 29472315, 2018). "In the present study, we found that high expression of AQP10 mRNA predicted a better prognosis in all ovarian cancer patients mostly with serous subtypes, well-differentiated pathological grade (grade I) and advanced stage (III + IV) ovarian cancer." (PMID 29472315, 2018). "Our results revealed that higher AQP0, AQP1, and AQP4 mRNA expression were correlated with poor OS, whereas higher AQP3, AQP5, AQP6, AQP8, AQP10, and AQP11 showed better OS in ovarian cancer patients." (PMID 29472315, 2018).
colon adenocarcinoma (1 paper, 2012). "Silencing of AQP10 expression with iRNA in the human colon adenocarcinoma Caco-2 cell line resulted in increased As(III) uptake, which suggests that AQP10 may be involved in intestinal absorption of As(III)." (PMID 22489166, 2012).
endometrioid ovarian cancer (1 paper, 2018). "However, the expression level of AQP10 was not correlated with endometrioid ovarian cancer, HR = 0.32 (0.03–3.08), P=0.3." (PMID 29472315, 2018).
enteritis (1 paper, 2016). Inflammation of the small intestine. "On the other hand, the downregulated expression of several AQPs (AQP1, AQP3, AQP4, AQP7, AQP8, AQP10 and AQP11) in the small and large intestines has been observed in the process of either enteritis or diarrhea." (PMID 27589719, 2016).
glioma (1 paper, 2024). A benign or malignant brain and spinal cord tumor that arises from glial cells (astrocytes, oligodendrocytes, ependymal cells). "The identification of AQP10 mutations suggests their potential relevance in glioma response to REGO treatment, warranting further investigation." (PMID 38534332, 2024).
ichthyosis (1 paper, 2024). Disorders of cornification that are characterized by visible scaling and/or hyperkeratosis of most or all of the skin. "In terms of maternal exposure to toluene, we observed that AQP10 was upregulated in mothers, which has been shown to exacerbate psoriasis-like ichthyosis by affecting keratinocytes." (PMID 39684538, 2024).
Sepsis (1 paper, 2024). Sepsis is defined as life-threatening organ dysfunction caused by a dysregulated host response to infection. "Recent studies suggest that AQPs, particularly aquaglyceroporins like AQP3, AQP7, AQP9, and AQP10, play pivotal roles in immune cell metabolism and offer new therapeutic avenues for sepsis treatment." (PMID 39544938, 2024).
serous ovarian cancer (1 paper, 2018). "Furthermore, high AQP10 mRNA expression was also correlated with better OS for serous ovarian cancer patients, HR = 0.71 (0.56–0.91), P=0.0073." (PMID 29472315, 2018).
cancer (3 papers, 2018 to 2022). A tumor composed of atypical neoplastic, often pleomorphic cells that invade other tissues. "For example, the results showed overexpression of AQP10 in cancer cells compared to normal cells; however, survival analysis indicated that overexpression of this gene increases the patient survival rate." (PMID 36254092, 2022). "The relationship between the expression levels of AQP7 and AQP10 and the prognosis of cancer remains ambiguous because there have been only a few attempts to examine AQP7 and AQP10 in cancer, and existing research was limited to the mRNA level." (PMID 35972604, 2022). "Moreover, the role of AQP10 in cancer has never been satisfactorily elucidated, which means that more research regarding AQP7 and AQP10 in cancer is needed." (PMID 35972604, 2022). "Different from other AQPs, there was no previous study about the role of AQP10 and AQP11 in human malignant tumors." (PMID 29472315, 2018).
bacterial infection (1 paper, 2020). "However, under stress and bacterial infection (e.g., Fusobacterium) conditions, AQP1, AQP3, AQP8, and AQP10 are mainly responsible for the maintaining of water homeostasis in the gastrointestinal tract." (PMID 32565721, 2020).
tumor (1 paper, 2021). "According to the GEPIA database, AQP1, AQP3, AQP4, and AQP9 were significantly expressed in LUAD tissues compared to normal lung tissues (p < 0.05), but some genes including AQP0, AQP5, AQP6, AQP7, AQP8, AQP10, and AQP11 were not differentially expressed between tumor and normal tissues." (PMID 34708074, 2021).
AQP10 also shares sentences with these, for which no sentence is quoted: metabolic disease (1 paper); psoriasis (1); Tremor (1).